TRPV1 (transient receptor potential cation channel subfamily V member 1)
Diseases named in the same sentence as TRPV1 in open-access papers (continued):
Sharing a sentence is not in itself a finding about the gene and the disease.
bone cancer (52 papers, 2009 to 2025). A primary or metastatic malignant neoplasm affecting the bone or articular cartilage. "TRPV1 has been found to be associated to bone cancer pain, as demonstrated by pharmacological inactivation of TRPV1 as well as disruption of the TRPV1 gene." (PMID 28649203, 2017). "Notably, we revealed that the underlying analgesic mechanisms of Metformin on bone cancer pain are in part via reducing the expression of TRPV1 and ASIC3." (PMID 34421611, 2021). "Loss of TRPV1 in mice abolished bone cancer–induced thermal hyperalgesia and PD-L1 analgesia." (PMID 32960817, 2020). "TRPV1 was first assessed in bone cancer pain in a 2005 study, via the injection of osteolytic sarcoma cells in mouse femurs." (PMID 39940997, 2025). "TRPV1 was initially evaluated in bone cancer pain in 2005, revealing that most sensory neurons in malignant bone expressed TRPV1, and subcutaneous treatment of its antagonist, JNJ-17203212, mitigated pain-related behaviors." (PMID 41148771, 2025). "Mice injected with Lewis lung cancer cells experience progressive bone cancer pain, which is markedly reduced in TRPV1-null animals." (PMID 38339399, 2024). "Several studies have shown that siRNA targeting TRPV1 can be used to treat dry eye disease, hyperalgesia induced by Complete Freund's Adjuvant and bone cancer pain." (PMID 37994506, 2024). "The combination of this TRPV1 antagonist and morphine has potent analgesic effects on bone cancer pain in mice." (PMID 39598351, 2024). "Several studies showed the inhibitory effect of intrathecal RTX only desensitizing TRPV1-expressing cells in the central nervous system in serious pain conditions including bone cancer models." (PMID 38791867, 2024). "ASIC3 is a pH sensor that responds to slight extracellular acidification, and was found obviously enhanced with TRPV1 in the DRG in rats of bone cancer models." (PMID 37250405, 2023). "In this mini review, we summarized the role and potential mechanism of DRG TRPV1 in bone cancer pain, including inflammatory mediators, endogenous formaldehyde, and other mechanisms." (PMID 36438444, 2022). "Although the mechanisms about TRPV1 regulation had been studied, target TRPV1 for bone cancer pain treatment is still limited because of the side effect." (PMID 36438444, 2022). "For instance, chronic morphine exposure increases TRPV1 expression in the spinal cord, DRG, and sciatic nerve, whereas blockade of TRPV1 with its antagonist SB366791 potentiates the analgesic effects of systemic morphine in mice with bone cancer." (PMID 35206575, 2022). "A study showed that the expression of TRPV1 in DRG was decreased in bone cancer, but capsazepine, an another antagonist of TRPV1, significantly alleviated the pain behavior by subcutaneous injection." (PMID 36438444, 2022). "Supporting the significance of TRPV1 in cancer pain, targeting TRPV1 with genetic and pharmacological approaches reduces pain in bone cancer, squamous cell carcinoma, and pancreatic cancer." (PMID 36138983, 2022). "Similar to our findings with tongue cancer and TG neurons, cancer-induced over expression of TRPV1 occurs in the DRG in a bone cancer pain model." (PMID 35260737, 2022). "In the present review, we summarize the role and potential mechanism of TRPV1 in DRG in bone cancer pain." (PMID 36438444, 2022). "In bone cancer pain model rats, IL-6 can up-regulate the expression of the TRPV1 protein in the dorsal root ganglia through the Janus kinase (JAK)/phosphatidylinositol 3-kinase (PI3K) pathway and participate in peripheral sensitization." (PMID 35800014, 2022). "The role of TRPV1 in bone cancer pain was demonstrated several years earlier when Mantyh and colleagues used pharmacologic antagonism and genetic disruption of TRPV1 to reverse spontaneous and functional pain in early and late stages of cancer progression." (PMID 35260737, 2022).
bone cancer (continued). "The mechanisms under TRPV1 regulation in DRG with bone cancer pain are complex, including inflammatory mediators, endogenous formaldehyde, and other mechanisms." (PMID 36438444, 2022). "In one of the most promising studies to date, selective ablation of TRPV1 fibers with intrathecal resiniferatoxin reversed cancer pain and restored function in a canine bone cancer model." (PMID 35260737, 2022). "A previous study from our lab showed that peripheral TGF-β1 signaling contributes to bone cancer pain via regulating transient receptor potential vanilloid-1 (TRPV1) in primary sensory neurons." (PMID 34076854, 2021). "Previously, we investigated the effects of TGF-β1 on the TRPV1 channel and neuronal excitability in primary sensory neurons, and its role in advanced bone cancer pain." (PMID 34076854, 2021). "In animal models, RTX treatment was found to induce the desensitization of TRPV1-expressing neurons and improved bone cancer pain, providing relief for several weeks in mice and dogs with advanced osteosarcoma." (PMID 35053150, 2021). "Resiniferatoxin (RTX) is another TRPV1 agonist that has shown promising effects for pain management, particularly in bone cancer." (PMID 35053150, 2021). "In rat advanced bone cancer, a robustly enhanced TRPV1 current and decreased desensitization rate to repetitive capsaicin application were observed in DRG neurons." (PMID 32960817, 2020). "In particular, selective KO of SHP-1 in DRG NaV1.8+ neurons significantly attenuated the inhibitory effects of PD-L1 on TRPV1 current and bone cancer pain, suggesting that SHP-1–inhibited TRPV1 in DRG neurons contributes to PD-L1’s analgesic effect." (PMID 32960817, 2020). "One important concept that has emerged over the past decade is that sensitization of transient receptor potential vanilloid 1 (TRPV1) plays an important role in driving bone cancer pain." (PMID 32960817, 2020). "The inhibition of PD-L1 (10 ng/mL) on TRPV1 currents by different doses of capsaicin was greater in bone cancer mice than that in sham mice (2-way RM ANOVA, treatments: F = 4.11, P = 0.04)." (PMID 32960817, 2020). "Consistent with our previous study in rats, whole-cell patch clamp recordings showed that capsaicin-induced (0.5–4.0 μM) TRPV1 currents in small-diameter (<25 μm) DRG neurons of bone cancer mice significantly increased as compared with those of sham ones." (PMID 32960817, 2020). "Together, our findings suggest that PD-L1/PD-1 signaling suppresses bone cancer pain via inhibition of TRPV1 activity." (PMID 32960817, 2020). "Our results also suggest that SHP-1 in sensory neurons is an endogenous pain inhibitor and delays the development of bone cancer pain via suppressing TRPV1 function." (PMID 32960817, 2020). "Conditioned deletion of SHP-1 in NaV1.8+ neurons aggravated bone cancer pain and diminished the inhibition of PD-L1 on TRPV1 currents and pain." (PMID 32960817, 2020). "To further clarify the role of TRPV1 in PD-L1–induced inhibition, we examined the effects of PD-L1 on bone cancer pain in TRPV1-knockout mice." (PMID 32960817, 2020). "Prior studies have shown the involvement of TRPV1 in rodent models of primary bone cancer pain, and TRPV1 antagonists significantly attenuated primary bone cancer-related pain behaviors." (PMID 29497363, 2018). "The expression of TRPV1, as well as the TRPV1-dependent currents, have been found to be enhanced upon the development of bone cancer in DRG neurons." (PMID 28649203, 2017). "Specifically, studies have looked at cancer pain using rodent bone cancer models, and found that TRPV1 is critical for the development of cutaneous thermal and mechanical sensitivity, as well as paw guarding behavior." (PMID 27854251, 2016). "TRPV1 is overexpressed in several chronic painful pathologies such as rheumatoid arthritis, osteoarthritis, bone cancer-induced pain and several neuropathies among others." (PMID 25257900, 2014).
bone cancer (continued). "In an osteosarcoma model of bone cancer, the percentage of TRPV1 positive neurons was increased by 7% in the DRG neurons of bone cancer mice compared to control mice." (PMID 24288084, 2012). "TRPV1 has been shown to mediate mechanical hypersensitivity after bone cancer, inflammation, nerve injury and sickle cell disease." (PMID 22927999, 2012). "It has been shown that TRPV1 is involved in the induction of bone cancer pain and is activated by direct phosphorylation via PKC pathway, particularly via PKCε." (PMID 21118579, 2010). "Our data suggest that cancer tissues directly secrete endogenous formaldehyde, and this formaldehyde at low concentration induces metastatic bone cancer pain through TRPV1 activation especially under tumor acidic environment." (PMID 20422007, 2010). "The present study aims to demonstrate that the tumor tissue-derived endogenous formaldehyde induces bone cancer pain via TRPV1 activation under tumor acidic environment." (PMID 20422007, 2010). "Following the development of bone cancer pain, the TRPV1 expression and capsaicin-evoked currents were up-regulated in rat DRG neurons at L4-6 segments." (PMID 21118579, 2010). "The present study provided further evidence that capsaicin-induced currents and expression of TRPV1 in DRG neurons were up-regulated in bone cancer rats." (PMID 21118579, 2010). "To elucidate the role of TRPV1 in bone cancer pain, we examined TRPV1 levels in the DRG at the L4-6 spinal segments 14 days after cancer cell implantation." (PMID 21118579, 2010). "Released by cancer cells and blood platelets, LPA not only promotes cancer cell proliferation but also contributes to the induction of bone cancer pain by enhancing TRPV1 activity in nociceptors." (PMID 21118579, 2010). "In animal models of pain, RTX has also been found useful in inflammatory pain, painful conditions affecting joints, and bone cancer pain by eliminating TRPV1 expressing peripheral nerve terminals or DRG neurons." (PMID 19753113, 2009). "Intriguingly, bone cancer induced by inoculation of carcinoma cells mainly results in altered mechanosensitivity, yet TRPV1 antagonists have been found to be useful." (PMID 19753113, 2009). "TRPV1 is also activated by both acidic and basic deviations from homeostatic pH; nonetheless, low pH (<5.9) is its main regulator, which is typical in the acidic microenvironment driven by bone cancer." (PMID 39940997, 2025). "In addition, the analgesic effects of morphine were enhanced in mice with bone cancer treated with the TRPV1 antagonist SB366791." (PMID 40549151, 2025). "It has been suggested that the PD‐L1/PD‐1 signaling pathway can exert analgesic effects on bone cancer pain in mice by inhibiting TRPV1 activity in primary sensory neurons via SHP‐1 to delay pain or by suppressing PD‐L1/CCl2‐mediated osteoclastogenesis and protecting against bone destruction." (PMID 38961264, 2024). "In the bone cancer pain model, the TRPV1 channel contributes to the sensitization of DRG neurons." (PMID 36438444, 2022). "In addition to experimental conditions, membrane TRPV1 plays more important role in bone cancer pain." (PMID 36438444, 2022). "In 2005, TRPV1 was first demonstrated to be involved in bone cancer pain." (PMID 36438444, 2022). "However, the role of TRPV1 in pain treatment still deserves attention, and studies in a rat model of bone cancer pain have found that metformin treatment can provide strong relief of mechanical abnormal pain by downregulating TRPV1 expression." (PMID 36081941, 2022). "Upregulation of membrane TRPV1 in DRG was also found in rats with bone cancer pain." (PMID 36438444, 2022). "TRPV1 is involved in PD-L1–induced inhibition of bone cancer pain." (PMID 32960817, 2020). "Next, we examined whether PD-L1–induced inhibition of bone cancer pain is partially achieved by modulating TRPV1." (PMID 32960817, 2020).
bone cancer (continued). "TRPV1–/– mice could still develop mechanical allodynia following the tumor inoculation, but the bone cancer–induced mechanical allodynia in TRPV1–/– mice was less than in WT mice (2-way RM ANOVA, treatment: F = 10.19, P = 0.002)." (PMID 32960817, 2020). "PD-L1 alleviates bone cancer pain via suppressing TRPV1 function." (PMID 32960817, 2020). "Furthermore, TRPV1-KO mice failed to develop thermal hyperalgesia in the tumor-affected limb, suggesting that increased TRPV1 expression and TRPV1 sensitivity contribute to bone cancer–induced pain hypersensitivity." (PMID 32960817, 2020). "Moreover, we try to reveal the effects of deleting SHP-1 in NaV1.8+ primary sensory neurons on PD-L1/PD-1 regulating TRPV1 activity and bone cancer pain." (PMID 32960817, 2020). "Thus, it is plausible that the analgesic effect of PD-L1 on bone cancer pain is achieved by inhibiting TRPV1 via PD-1 expressed by DRG neurons." (PMID 32960817, 2020). "Conversely, TRPV1 activation may promote proinflammatory and pro-nociceptive effects as described in animal models of peripheral neuropathic pain and bone cancer pain, and in human osteoarthritis and rheumatoid arthritis." (PMID 30761069, 2019). "However, several studies in the recent past have now suggested the involvement of TRPV1 in mechanical pain hypersensitivity in the context of a number of painful pathologies, such as inflammation, nerve injury, sickle cell disease and primary bone cancers." (PMID 29497363, 2018). "Finally, JAK/PI3K-dependent TRPV1 up-regulation has been reported to be involved in peripheral sensitization and bone cancer-induced pain evoked by interleukin-6." (PMID 28649203, 2017). "Furthermore, the TRPV1 antagonist SB366791 has been reported to potentiate the analgesic effect of intraperitoneal administration of morphine in a mouse model of bone cancer pain." (PMID 28649203, 2017). "The role of TRPV1 in bone cancer pain has been widely investigated." (PMID 28649203, 2017). "Selective inhibition of TRPV1 channel attenuated bone cancer pain in the mouse." (PMID 27483289, 2016). "Additionally, preclinical trials of intrathecal resiniferatoxin, the potent TRPV1 agonist, have shown it to be very effective in a canine model of bone cancer pain." (PMID 27854251, 2016). "This peptide is able to reduce inflammatory potentiation of TRPV1 in sensory neurons reducing TRPV1 membrane rapid translocation, and has demonstrated successful analgesic effect in animal models of inflammatory, neuropathic and bone-cancer induced pain." (PMID 25257900, 2014). "In this situation, endogenous formaldehyde (although its concentration was ≤3 mM) from cancer tissues could induce metastatic bone cancer pain through activation of ion channels in nerve fibers especially under tumor acidic environment, for example TRPV1." (PMID 23516587, 2013). "However, in a bone cancer pain model, TRPV1 knock-out mice displayed approximately 40–50% less spontaneous pain behaviors and palpation-induced flinching compared to wild-type mice." (PMID 24288084, 2012). "A recent study showed that activation of TRPV1 is involved in bone cancer pain." (PMID 24288041, 2011). "0.01 μM LPA couldn't potentiate the TRPV1 current induced by 0.5 μM capsaicin in all of the DRG neurons (n = 24) in bone cancer rats." (PMID 21118579, 2010). "Therefore, in the present study, we postulated that excessive cancer tissue-derived endogenous formaldehyde induces bone cancer pain via TRPV1 especially under an acidic tumor microenvironment." (PMID 20422007, 2010). "LPA potentiates TRPV1 current via a PKCε-dependent pathway in DRG neurons of rats with bone cancer, which may be a novel peripheral mechanism underlying the induction of bone cancer pain." (PMID 21118579, 2010). "TRPV1 antagonists and formaldehyde scavengers attenuated bone cancer pain responses." (PMID 20422007, 2010). "TRPV1 antagonists attenuated endogenous formaldehyde-induced bone cancer pain behaviors." (PMID 20422007, 2010).
bone cancer (continued). "In the present study we examined whether an interaction between LPA receptor LPA1 and TRPV1 in dorsal root ganglion (DRG) neurons contributes to the development of bone cancer pain." (PMID 21118579, 2010). "Suitably, TRPV1 knockdown through an adeno-associated virus (AAV)-mediated short-interfering RNA (siRNA) reduced mechanical allodynia and thermal hyperalgesia in a rat model of bone cancer pain, with concomitant under-expression of neuroinflammatory mediators in the animals’ spinal cords." (PMID 39940997, 2025). "Moreover, inhibition of TRPV1 activity suppressed bone cancer pain through PD‐L1/PD‐1 signaling." (PMID 38961264, 2024). "Previous studies also showed that antagonism of TRPV1 relieves thermal and/or mechanical hypersensitivity in multiple models of inflammation induced by ultraviolet B, complete Freund’s adjuvant, and postoperative or bone cancer pain in rodent models and humans." (PMID 35206575, 2022). "In the future, target TRPV1 in DRG might be a better choice for bone cancer pain treatment." (PMID 36438444, 2022). "However, whether ASIC3/TRPV1 is involved in the analgesic effect of Metformin on bone cancer pain remains unclear." (PMID 34421611, 2021). "Furthermore, targeting TRPV1 receptors could also be beneficial in reducing cancer pain, due to the well-known analgesic properties of TRPV1 stimulation in animal models with bone cancer pain." (PMID 31003519, 2019). "Furthermore, potentiation of TRPV1 by LPA was examined in the bone cancer state." (PMID 21118579, 2010). "Given expression of LPA1 and TRPV1 in the DRG neurons, the present study focused on whether LPA1 is involved in bone cancer pain via cross-talking with TRPV1 and the possible signal pathways in the peripheral mechanism underlying bone cancer pain." (PMID 21118579, 2010). "Bone cancer induces mechanical bone deformation and local tissue acidosis which may activate nociceptors via multiple molecular mechanisms, particularly by activation of the capsaicin receptor, transient receptor potential vanilloid (TRPV1)." (PMID 21118579, 2010). "Therefore, it seems that PKCε, but not PKA, phosphorylation may be a common mechanism in which activation of LPA1 and NK-1 potentiates TRPV1 in DRG nociceptive neurons contributing to bone cancer pain and neuropathic pain." (PMID 21118579, 2010). "The TRPV1 antagonist SB366791, at doses of 0.3 and 1.0 mg/kg, significantly reduced spontaneous flinches in mice with bone cancer pain." (PMID 39598351, 2024). "The boosted expression of TRPA1-, TRPV1-, and TRPV4-immunoreactive cells in ipsilateral L4–5 DRG due to bone cancer proliferation was inhibited by LTTL gel application." (PMID 38730655, 2024). "In a rat model of bone cancer pain (SCC158 carcinoma cells injected into the hind paw), the first generation TRPV1 antagonist capsazepine blocked both mechanical and thermal hyperalgesia." (PMID 38339399, 2024). "In a rat model of bone cancer pain, IGF1 was found to up-regulate TRPV1 expression in sensory afferents." (PMID 38339399, 2024). "IL-6, for instance, induces the functional upregulation of TRPV1 in DRG neurons through the activation of the JAK/PI3K signaling pathway, contributing to the pathogenesis of bone cancer pain." (PMID 37664239, 2023). "In bone cancer pain rats, LPA potentiated TRPV1 current via a protein kinase C (PKC)-dependent pathway in DRG neurons." (PMID 36438444, 2022). "Over the past years, transient receptor potential channels (TRPs), especially TRP vanilloid 1 (TRPV1) in dorsal root ganglion (DRG), have been considered to be involved in bone cancer pain." (PMID 36438444, 2022). "Here, we further found that PD-L1/PD-1 signaling inhibited TRPV1 activity via SHP-1 in primary sensory neurons and thereby suppressed and delayed the development of bone cancer pain in mice." (PMID 32960817, 2020).